ATG16L1 (autophagy related 16 like 1)
Diseases named in the same sentence as ATG16L1 in open-access papers (continued):
Sharing a sentence is not in itself a finding about the gene and the disease.
Crohn disease (continued). "In pure cells with NOD2 shifter mutations associated with Crohn's disease, mutant NOD2 fails to recruit ATG16L1 to the plasma membrane, and autophagosome encapsulation of invading bacteria is impaired." (PMID 39883213, 2024). "The production of IL-1β and IL-18 is increased in the absence of functional ATG16L1 in a mouse model of Crohn’s disease." (PMID 25409294, 2014). "This phenomenon showed that ATG16L1 played an important role in the course of the disease, and the relationship between ATG16L1 and CNTNAP3 showed that CNTNAP3 might be of importance in autophagy process of Crohn's disease." (PMID 25883416, 2015). "A knock down of Atg16l1 in mice induces a phenotype similar, but not identical, to Crohn's disease." (PMID 23982303, 2014). "Besides, autophagy has been recognized to have an anti-inflammatory action since the production of interleukine (IL)-1β and IL-18 was increased in the absence of functional ATG16L1 (a key protein of the ubiquitin-like conjugation system Atg5-Atg12 ~ Atg16) in a mouse model of Crohn’s disease." (PMID 25169902, 2014). "In the absence of ATG16L1, MNV triggers intestinal pathologies in mice through up-regulation of IFN-γ and TNF such as Crohn’s disease, and these findings can be extrapolated to human biology as well." (PMID 36288309, 2022).
colitis (48 papers, 2009 to 2026). Inflammation of the colon. "Deficiency of ATG16L1 in hematopoietic cells resulted in increased susceptibility to DSS-induced colitis, suggesting a critical function for ATG16L1 in the regulation of intestinal inflammation." (PMID 40842999, 2025). "Infection of ATG16L1-deficient mice with a persistent strain of murine norovirus renders these mice highly susceptible to dextran sulfate sodium colitis." (PMID 39464882, 2024). "Important risk variants in murine models as well as IBD patients impair P cell function, leading to colitis; notably, the autophagy gene ATG16L1 and NOD2 mutations, with disturbed secretory P cells, result in antibacterial autophagy defects." (PMID 37686376, 2023). "ATG16L1 deficiency in hematopoietic or myeloid cells renders mice more susceptible to experimental colitis due to hyperactivation of pan inflammatory responses including the inflammasome and IL1β/IL18 processing." (PMID 37425656, 2022). "Mice lacking Atg16L1 in hematopoietic cells revealed a strong susceptibility to acute colitis induced by dextran sulfate sodium, implying that Atg16L1 protects mice from intestinal inflammation." (PMID 34019141, 2021). "Deficiency of ATG16L1 in hematopoietic cells resulted in an increased susceptibility to dextran sulfate sodium (DSS)-induced colitis, suggesting an essential role for ATG16L1 in the control of intestinal inflammation." (PMID 30669622, 2019). "Different autophagy deficient mice models such as Atg16L1 deficient chimeric mice, myeloid Atg16L1 deficient mice, colonic epithelial cell-specific Atg7 conditional KO mice, and Atg4B null mice all exhibit exacerbated colitis induced by DSS." (PMID 30764829, 2019). "In the murine norovirus infection model, IEC specific Atg16L1 KO mice are more susceptible to DSS induced colitis." (PMID 30764829, 2019). "Myeloid cells can also play a role in inflammation during IBD, and loss of ATG16L1 in myeloid and dendritic cells leads to enhanced colitis and increased production of inflammatory cytokines." (PMID 30666959, 2019). "Treatment with neutralizing antibodies for these cytokines reduce the susceptibility of Atg16L1 deficient mice to DSS induced colitis, indicating the importance of Atg16L1 in the suppression of intestinal inflammation." (PMID 30764829, 2019). "It has been reported that mice lacking essential components of the autophagic machinery, such as the autophagy-related 16-like 1 (Atg16L1) are highly susceptible to colitis." (PMID 26437418, 2015). "Moreover, conditional deletion of Atg16l1 in IECs evokes patchy transmural enteritis that arises consequent to endoplasmic reticulum (ER) stress and provides susceptibility to toxic colitis." (PMID 41382985, 2026). "Studies in mice with myeloid ATG16L1 deficiency have shown that ATG16L1 deficiency leads to an increased inflammatory response as well as an increase in colitis-causing bacteria, suggesting that ATG16L1 deficiency leads to altered macrophage function, which exacerbates CD." (PMID 40842999, 2025). "Fetal liver cell chimeric mice with Atg16L1 deficient hematopoietic cells have increased susceptibility to DSS colitis as demonstrated by acute weight loss and severe distal colon inflammation suggesting a protective role of autophagy in the suppression of colitis." (PMID 30764829, 2019). "Another study using mice with myeloid ATG16L1 deficiency showed exacerbated colitis with upregulated proinflammatory responses as well as increased colitogenic bacteria, indicating that ATG16L1 deficiency results in alterations in macrophage function that affect the severity of CD." (PMID 30669622, 2019). "Likewise, DCs with autophagy-related 16-like 1 (Atg16L1) gene deficiency showed excessive production of reactive oxygen species and abnormal antigen processing under colitis exposure." (PMID 29326712, 2017).
colitis (continued). "Additionally, previous studies demonstrate that a deficiency in Atg16l1 results in an increased susceptibility to experimental colitis, abnormal appearance and distribution of Paneth cell granules, and altered mitochondria." (PMID 26484345, 2015). "However, Atg16L1-deficient chimeric mice administered 5% DSS for 7 days exhibited a marked exacerbation of colitis with reduced survival." (PMID 24137160, 2013). "Furthermore, mice with defective Atg16L1 protein in the haematopoietic system were highly susceptible to dextran sodium sulphate- (DSS-) induced colitis, again indicating the crucial role of autophagy in the pathogenesis of IBD." (PMID 22291845, 2012). "Furthermore, it was shown that ER stress and dysregulated autophagy process act synergistically to promote UC development, following the observation that mice deficient for both Atg16L1 and Xbp1 developed an increased intestinal inflammation and a severe form of colitis." (PMID 32659925, 2020). "In the colon tissue of mice with DSS-induced colitis, the expressions of P62, mTOR, and p-mTOR increased, while ATG16L1 and LC3II/I decreased." (PMID 40534879, 2025). "Our data demonstrate that ATG16L1-deficiency in DCs promotes the development of LP CD8+ TRM cells and increases susceptibility to colitis which can be attenuated by stimulation of the TLR7 signaling pathway." (PMID 39464882, 2024). "ATG16L1-deficieny in myeloid cells or DCs resulted in a similar phenotype than Tlr7-/- mice, with increased susceptibility to DSS colitis, increased disease activity index, histoscores, and increased secretion of IFN-γ and TNF-α." (PMID 39464882, 2024). "Our data demonstrate that ATG16L1-deficiency in myeloid and dendritic cells leads to an increase in LP TRM and consequently to increased susceptibility to colitis by impairing the recognition of enteric viruses by TLR7." (PMID 39464882, 2024). "In mice with inactivated IKKα kinase, loss of IKKα function resulted in the reduced stability of ATG16L1, which induced UPR and significantly impaired intestinal epithelial regeneration in mice with acute colitis model." (PMID 37168865, 2023). "The IBD-associated genes ATG16L1 and NOD2 are crucial for OMV-mediated activation of colitis protection." (PMID 37841244, 2023). "The percentage of ATG16L1 or LC3-positive cells increased significantly in colitis tissues of rapamycin-treated mice than TNBS-treated mice and control mice." (PMID 36032781, 2022). "Induction of remission was associated with the accumulation of colonic DCs expressing ATG16L1 in CD patients, which was consistent with aggregated DSS-induced colitis in mice with DC-specific Atg16l1 deletion." (PMID 33935757, 2021). "This exaggerated IEC apoptosis is reported to be due to increased susceptibility to TNF-α and, as expected, TNF-α inhibition reduces the colitis severity in Atg16L1 conditionally KO mice." (PMID 30764829, 2019). "In another model of colitis induced by Helicobacter hepaticus, mice with a deletion of ATG16L1 in IECs had worse histopathology than their littermates." (PMID 31164887, 2019). "High-resolution mini-endoscopy revealed a thickened and granular mucosal colon surface with altered vascularization, indicative of colitis in A20/Atg16l1 dKO mice." (PMID 31015422, 2019). "Downregulation of autophagy in mice by deletion of the ATG16L1 gene, which is essential for autophagy, resulted in inflammasome activation and increased severity of experimental colitis." (PMID 29720937, 2018). "Deletion of autophagy‐related gene ATG16L1 in CD11c+ cells results in more severe DSS‐induced colitis in mice." (PMID 30338217, 2018). "ATG16L1−/− mice show high IL-1βand IL-18 levels in sera in response to LPS stimulation or during colitis." (PMID 27821816, 2016). "The study showed that intestinal epithelial VDR deletion impaired antimicrobial function of Paneth cells by downregulation of Atg16l1 and lysozyme, thus causing increased susceptibility to DSS-induced colitis." (PMID 28119697, 2016).
colitis (continued). "For example, mice hypomorphic for Atg16L1 need a viral infection trigger for inducing colitis-like pathology." (PMID 24137160, 2013). "Similarly, to the phenotype we observed in Tlr7-/- mice, myeloid- and DC-specific deletion of ATG16L1 (Atg16l1ΔLyz2 and Atg16l1ΔCd11c mice) resulted also in elevated LP CD8+ TRM cells and increased susceptibility to DSS colitis." (PMID 39464882, 2024). "Consequently, our data demonstrate that ATG16L1-deficiency in myeloid cells promotes LP TRM cell accumulation and increases the susceptibility to colitis by impairing the activation of TLR7 signaling in response to RNA viruses." (PMID 39464882, 2024). "Mice with dendritic cell ATG16L1 deletion showed increased susceptibility to infection in DSS-induced colitis but not to S. typhimurium." (PMID 37168865, 2023). "Animals lacking ATG16L1 in the epithelium were more susceptible to DSS-induced colitis, and the pathology was exacerbated when these animals were infected with murine norovirus (MNV)." (PMID 31164887, 2019). "Furthermore, a defect in either ATG16L1 or IRGM has been associated with reduced Paneth cell function, increased susceptibility to bacterial infection, and development of colitis." (PMID 26484345, 2015). "Mice lacking Atg16L1 in hematopoietic cells are highly susceptible to dextran sulfate sodium (DSS)-induced acute colitis." (PMID 24260541, 2013). "In addition, deletion of the autophagy gene ATG16L1 in mice resulted in inflammasome activation and more severe experimental colitis." (PMID 21490934, 2011). "Mice lacking Atg16L1 are more susceptible to chemically-induced colitis than wild-type animals subject of the same stress." (PMID 19709415, 2009). "Furthermore, Atg16L1-deficient fetal liver chimeric mice displayed normal bacterial colonization of the colon and no indication of spontaneous colitis." (PMID 24137160, 2013). "In conclusion, we demonstrated that relation between ATG16L1 and TLR7 plays an important role in maintaining immune response to intestinal viruses and protects against colitis." (PMID 39464882, 2024). "Our findings suggest an important convergence of the ATG16L1 and TLR7 signaling pathways in myeloid cell-mediated immune responses to intestinal viruses and protection against the development of colitis." (PMID 39464882, 2024). "Previous studies have demonstrated the involvement of genetic variations of autophagy genes, including ATG16L1 and IRGM, in the pathogenesis of colitis." (PMID 30669622, 2019). "For example, Bacteroides fragilis can secrete capsular polysaccharide A to induce expression of interleukin-10 from regulatory T cells and protect mucous from colitis in a NOD2- and ATG16L1-dependent way." (PMID 29404425, 2018). "Additionally, research shows increased P62, mTOR, and p-mTOR levels in experimental colitis, while LC3B and ATG16L1 levels are reduced." (PMID 40534879, 2025). "ATG16L1 T300A transgenic mice did not exhibit protection from 2,4-dinitrobenzene sulfonic acid-induced colitis." (PMID 37841244, 2023). "In fact, compared with Atg16L1[ΔIEC] or Xbp1[ΔIEC] mice, mice lacking Atg16L1 and Xbp1 (Atg16l1[ΔIEC]Xbp1[ΔIEC]) develop more severe colitis." (PMID 34588980, 2021). "Similarly, western blotting and immunohistochemical staining showed decreased expression of Erbin, increased expression of LC3B, decreased expressions of ATG16L1 and ATG2A in DSS-induced colitis mice and IL-10-/- mice compared with that in control mice." (PMID 29552291, 2018). "We also examined mice lacking Atg16l1 or A20 in intestinal epithelial cells (IECs) because these genes encode important negative regulators of TNF-induced cell death, and their mutation is associated with colitis in humans." (PMID 31101885, 2020). "However, Atg16l1 hypomorphic mice did not exhibit signs of spontaneous intestinal inflammation, although they showed increased susceptibility to DSS-induced colitis." (PMID 27446072, 2016).
inflammatory bowel disease (48 papers, 2012 to 2026). A spectrum of small and large bowel inflammatory diseases of unknown etiology. "The clinical relevance of this mechanism is underscored by human genetic studies associating ATG16L1 polymorphisms (e.g., T300A) with exaggerated IL-1β and IL-6 production in inflammatory bowel disease." (PMID 41522448, 2025). "A SNP in ATG16L1 (T300A) is a major risk variant for Crohn’s disease (CD), an inflammatory bowel disease (IBD)." (PMID 31450711, 2019). "Atg16L1 mutations are associated with inflammatory bowel disease (IBD) in humans and patients with such mutations have a decreased frequency of regulatory CD4+ T cells." (PMID 30542350, 2018). "Accordingly, mice with Atg16L1 deficient dendritic cells and some macrophage populations develop inflammatory bowel disease." (PMID 30542350, 2018). "It is still possible that under some contexts, such as inflammatory bowel disease, an increased ATG16L1 cleavage influenced by the T300A polymorphism may affect ATG16L1 WD40 CTD‐dependent non‐canonical autophagy." (PMID 29317426, 2018). "A polymorphism in the autophagy gene Atg16l1 is associated with susceptibility to inflammatory bowel disease (IBD); however, it remains unclear how autophagy contributes to intestinal immune homeostasis." (PMID 26910010, 2016). "Since genome-wide association studies have implicated that autophagy related 16-like 1 (ATG16L1) gene polymorphisms are associated with risk of inflammatory bowel disease, previous researchers have established autophagy-deficiency in an intestinal epithelial cell model using Villin-Cre mice." (PMID 26496833, 2015). "Genetic predisposition, particularly through polymorphisms in autophagy‐related genes like ATG16L1, is a critical determinant of susceptibility to both H. pylori infection and Inflammatory Bowel Disease (IBD)." (PMID 41473023, 2025). "A coding variant of the inflammatory bowel disease (IBD) risk gene ATG16L1 has been associated with defective autophagy and deregulation of endoplasmic reticulum (ER) function." (PMID 30254094, 2018). "In humans, polymorphisms in several autophagy-related genes, including IRGM, LRRK2, SMURF1 and ATG16L1, leading to autophagy deficiency are linked to inflammatory bowel disease (IBD) susceptibility." (PMID 28916785, 2017). "An analysis of 30 606 inflammatory bowel disease (IBD) patients revealed that the ATG16L1 variant rs2241880 is a persistent risk factor for the development of IBD and may influence patient prognosis." (PMID 40211890, 2025). "Both, Atg16l1 and Xbp1 are known risk genes for inflammatory bowel disease (IBD)." (PMID 41057521, 2025). "In inflammatory bowel disease, ATG16L1 has been shown to inhibit RIPK3-dependent necroptosis, thereby activating mitophagy, maintaining mitochondrial integrity, and reducing inflammation." (PMID 41567193, 2025). "For example, mutations in gene ATG16L1 promote the production of IL-22 in the intestinal epithelium through cGAS/STING pathway, which result in excessive epithelial cell death and inflammatory bowel disease (IBD)." (PMID 35006429, 2020). "Specifically, genes such as ATG16L1, ATG5, ATG10 or ATG7, accumulate multiple SNPs linked to pathologies that include cancer, neurological disorders, or inflammatory bowel diseases." (PMID 33147747, 2020). "This is the case, for example, of rs2241880, the threonine-to-alanine substitution at amino acid position 300 of ATG16L1 (T300A) that has been intensively analyzed in the context of inflammatory bowel diseases." (PMID 33147747, 2020). "ATG16L1 also regulates T cell activation and differentiation in some autoimmune diseases, such as inflammatory bowel disease and SLE59,60." (PMID 30988391, 2019). "Genome-wide association studies (GWAS) linking polymorphisms in ATG16L1 with susceptibility to inflammatory bowel disease (IBD) have prompted mucosal immunologists to investigate the functional roles of macroautophagy/autophagy in different cell types in the gut." (PMID 29799774, 2018).
inflammatory bowel disease (continued). "Dysfuntion in autophagy genes such as ATG16L1, IRGM, and LRRK2, are emerging as potential susceptibility traits in patients with inflammatory bowel disease." (PMID 22363587, 2012). "TNFAIP3 may also impact inflammatory bowel diseases by interacting with autophagy-related 16-like 1 (ATG16L1) protein." (PMID 39125844, 2024). "Consistent with studies of the effects of human ATG16L1 polymorphisms, models exhibit morphological abnormalities in both Paneth and goblet cells, but do not develop spontaneous intestinal permeability or inflammatory bowel disease." (PMID 33818130, 2021). "Although intestinal permeability is a common inciting cause of inflammatory bowel disease, human patients carrying the Atg16l1 T300A susceptibility variant do not have inherent increases in intestinal permeability." (PMID 33818130, 2021). "Other autophagy gene mutations (autophagy-related 16-like 1 (ATG16L1) and immunity-related GTPase family M protein (IRGM) that can predispose to inflammatory bowel disease (IBD) are also presented in the literature." (PMID 39000043, 2024). "The double knockout of A20 and ATG16L1 in the intestinal epithelium results in spontaneous inflammatory bowel disease (IBD)-like pathology." (PMID 33919439, 2021). "The Inflammatory Bowel Disease (IBD) Panel, which includes NOD2, IL23R, and ATG16L1 genes along with CYP2C19, which are associated with IBD severity and susceptibility can aid in defining genetic risk and tailoring treatment for patients suffering from Crohn’s disease and ulcerative colitis." (PMID 38420192, 2024). "Loss of ATG16L1 or VDR expression impairs autophagy, resulting in cellular dysfunction, and has been associated with intestinal dysbiosis and inflammatory diseases, including inflammatory bowel disease (IBD)." (PMID 30828578, 2018). "MNV-4 alters disease progression in a mouse model of bacterially-induced inflammatory bowel disease (IBD), and infection with the MNV strain CR6 induced intestinal inflammation resembling Crohn’s disease in mice with a genetically susceptible background (ATG16L1)." (PMID 24451302, 2013). "We previously examined the effects of the NOD2 and ATG16L1 polymorphisms on ileal microbial composition in 1) ileal CD subjects undergoing initial ileal resection, 2) IBD colitis without ileitis (predominantly ulcerative colitis) subjects and 3) subjects without inflammatory bowel disease (non-IBD)." (PMID 30818349, 2019).